CCSER2 (coiled-coil serine rich protein 2)
Description:
Microtubule-binding protein which might play a role in microtubule bundling.
Synonyms: FAM190B; KIAA1128; Gcap14; bA486O22.1
Tractability: PROTAC: ubiquitination databases record sites on it; its protein half-life has been measured.
Gene: Protein-coding gene on chromosome 10 (84,328,586 to 84,518,521, forward strand). Ensembl gene ENSG00000107771.
Subcellular location: Cytoplasm, cytoskeleton
Subcellular location (Human Protein Atlas): Cytosol; Nucleoplasm
Gene Ontology:
Molecular function: protein binding; microtubule binding
Biological process: microtubule bundle formation
Cellular component: microtubule cytoskeleton; cytoskeleton
Genetic constraint (gnomAD): Loss-of-function variants: 28 observed, 65.15 expected, observed/expected ratio (o/e) 0.43, 90% interval 0.32 to 0.59. The upper end of that interval is the gene's LOEUF score, 0.59, which puts it in group 2 of 6, group 1 being the genes least tolerant of losing a copy. Missense variants: 1,013 observed, 1,077.4 expected, observed/expected ratio (o/e) 0.94, 90% interval 0.89 to 0.99. Synonymous variants: 371 observed, 382.54 expected, observed/expected ratio (o/e) 0.97, 90% interval 0.89 to 1.06.
Homologues: Orthologues: chimpanzee CCSER2 (99% identical), macaque CCSER2 (97% identical), pig CCSER2 (88% identical), rabbit CCSER2 (88% identical), rat Ccser2 (80% identical), guinea pig CCSER2 (74% identical), dog CCSER2 (69% identical), mouse Ccser2 (65% identical), tropical clawed frog ccser2 (42% identical), zebrafish ccser2a (26% identical), zebrafish ccser2b (19% identical). Paralogues in human: CCSER1 (14% identical).
Diseases named in the same sentence as CCSER2 in open-access papers:
CCSER2 is named in the same sentence as 7 diseases in open-access papers, as found by Europe PMC text mining. Sharing a sentence is not in itself a finding about the gene and the disease. The quoted sentences say what the papers report.
breast carcinoma (2 papers, 2020 to 2023). "Here, we report the identification and analysis of Ccser2 as a new + TIP in human breast cancer MCF-7 cells." (PMID 37684684, 2023). "Based on molecular links between MTs and breast cancer, we further sought to analyze Ccser2 expressed in a human breast cancer cell line, MCF-7." (PMID 37684684, 2023). "CCSER2 is the most stable gene (from our selected reference genes) identified in the database for Luminal A sub-type breast cancer." (PMID 32977762, 2020).
mastitis (1 paper, 2021). Inflammation of breast tissue during lactation or postpartum due to an obstructed duct or infection. "Coiled-coil serine rich protein 2 is under selection and associated with mastitis in Holstein dairy cows." (PMID 32777913, 2021).
tumor (2 papers, 2023). "Six genes, and in particular CCSER2, appeared to be good candidates to play a role as tumor suppressor genes in NB and possible targets for future therapeutic interventions." (PMID 37046696, 2023). "It would be interesting to investigate Ccser2 in other malignant tumor cells." (PMID 37684684, 2023). "Six genes CCSER2, AGAP11, IFIT2, PAPSS2, PCGF5, and NUDT9P1 were observed to have potential NB tumor suppressor activity since their low expression was associated with poor survival even after correction for confounding by other prognostic factors (MYCN status, age at diagnosis, stage of disease)." (PMID 37046696, 2023). "CCSER2 has not yet been described as a tumor suppressor gene, however, there is a good chance that it could be involved in the development or progression of NB, even if functional studies will be needed to define this role." (PMID 37046696, 2023).
cancer (1 paper, 2023). A tumor composed of atypical neoplastic, often pleomorphic cells that invade other tissues. "Ccser2 has been suggested to be expressed in many cancer cell lines originating from various tissues (CCSER2 in The Human Protein Atlas." (PMID 37684684, 2023).
CCSER2 also shares sentences with these, for which no sentence is quoted: Cowden syndrome (1 paper); juvenile polyposis syndrome (1); papillary renal cell carcinoma (1).